MTOR (mechanistic target of rapamycin kinase)
Diseases named in the same sentence as MTOR in open-access papers (continued):
Sharing a sentence is not in itself a finding about the gene and the disease.
cancer (continued). "Therefore, combination therapy with both mTOR and MNK inhibitors might be an effective therapeutic strategy to enhance mTOR-targeted cancer therapy in NSCLC." (PMID 32340135, 2020). "As the mTOR pathway is also highly active in proliferating cancer cells, it will be crucial to determine whether the activation of the mTOR pathway by resistance exercise does not exacerbate tumor proliferation and metastasis development." (PMID 31936342, 2020). "On the other hand, ERK1 and p-ERK1/2 proteins are well known to be activated in cancer, playing an important role in cancer cell proliferation, growth, and cell viability, either dependently or independently of the activation of AKT or mTOR proteins in the cells." (PMID 31948009, 2020). "Targeting mTOR and MNK simultaneously may increase efficacy against cancer." (PMID 32340135, 2020). "Significant expression abnormalities were detected in many genes included in well-known several cancer-related pathways, such as RTKs, Mitogen-activated protein (MAP) kinase, Janus kinase (JAK)/signal transducer and activator of transcription (STAT), and PI3K/AKT/mTOR." (PMID 32702887, 2020). "Interestingly, several pro-inflammatory cytokines, acting in an autocrine fashion on cancer cells, besides STAT3, may activate other pro-oncogenic pathways such as mTOR, crucial for cancer survival." (PMID 32754441, 2020). "Since PHLDA3 regulates the PI3K/Akt/mTOR pathway by suppressing Akt activation, it is possible that new drugs that mimic PHLDA3 function may show efficacy not only in PanNETs but also in other cancers in which Akt is highly activated." (PMID 32521808, 2020). "In addition, in cancer cells, ER stress-induced activation of ATF4 downstream of eIF2α phosphorylation was reported to promote autophagy by activating DDIT4, which in turn increases eEF2K activity through mTOR inhibition." (PMID 32059483, 2020). "Although immunosuppression is typically undesirable in cancer treatment because it decreases immune surveillance, there is little evidence suggesting that using mTOR inhibitors as a monotherapy could promote tumor growth." (PMID 33037092, 2020). "Given the importance of RAS–RAF–MEK and RAS–PI3K–AKT signaling in cancer, we sought to confirm their differential regulation of TAZ by pharmacological inhibition with target-specific inhibitors—PD184352 (a MEK inhibitor), triciribine (an AKT inhibitor), and rapamycin (a mTOR inhibitor)." (PMID 32561852, 2020). "YTHDF3 was enriched in mTOR signaling pathway (NES = 1.98, p = 0.021), neurotrophin signaling pathway (NES = 1.98, p = 0.023), Notch signaling pathway (NES = 2.10, p = 0.012), pathways in cancer (NES = 1.84, p = 0.047) and Wnt signaling pathway (NES = 1.86, p = 0.042)." (PMID 33362863, 2020). "Whereas the therapeutic benefits of MET in many cancer types are known to be mediated by the inhibition of the PI3K/AKT/mTOR-signaling pathways, the anti-cancer effects and signaling mechanisms of MET in non-diabetic vs. diabetic women with EC have not been fully characterized." (PMID 32046384, 2020). "Additionally, attenuated proliferation could be the result of reduced mTOR activity, which was proved in CAIX suppressed/inhibited cancer cells." (PMID 32560271, 2020). "In the same cancer cells resistant to etoposide (A549RT-eto), feroniellin A (FERO; 0.05–1 mM), a novel furanocoumarin, induced autophagy, characterized by the conversion of LC3 I, the induction of GFP-LC3 puncta structures, the increase in Beclin 1 and ATG5 expression and the inhibition of mTOR." (PMID 32927836, 2020). "In addition to playing a role in the biological processes described as above, CRNDE has been reported to be regulated by insulin and insulin-like growth factors (IGFs) through the PI3K/Akt/mTOR and Raf/MAPK pathways, thereby affecting glucose metabolism and cancer microenvironment." (PMID 32435153, 2020).
cancer (continued). "The Cancer Genome Atlas dataset, an L1000 microarray with Gene Set Enrichment Analysis (GSEA) analysis, Western blot analysis and an animal model were used to study the activity of the AKT/mTOR pathway in response to the synergistic effects of neoadjuvant metformin combined with chemotherapy." (PMID 32825834, 2020). "Recent studies have shown that mTOR inhibition is not effective as monotherapy; several cancer types bypass this inhibition by upregulating glycolysis, while suppression of glycolysis is bypassed by hyperactivation of mTOR and subsequent metabolic reprogramming." (PMID 32665551, 2020). "Those four miRNAs, namely, miR-99a, miR-125b, miR-188, and miR-223, may regulate several signaling pathways, including the mTOR signaling pathway, signaling pathways regulating the pluripotency of stem cells, and the MAPK signaling pathway, as well as microRNAs in cancer." (PMID 33335254, 2020). "Given the plethora of essential biological processes controlled by mTOR, it is not surprising that mTOR-signaling dysfunctions have been reported in many pathological conditions including cancer, metabolic disorders, and neuromuscular and neurological diseases." (PMID 32620110, 2020). "mTOR is an intracellular serine/threonine kinase involved in the PI3K/AKT pathway, that indirectly regulates ribosomal translation of mRNA into proteins necessary for cell growth, cell cycle progression, and cell metabolism, making it an excellent target for cancer cells to hijack." (PMID 32676162, 2020). "Moreover, crosstalk regulation between the mTOR pathway and the CXCL12/CXCR4 axis suggests that mTORC1 silencing is sufficient to decrease CXCR4-mediated cancer cell migration, and inhibition of mTORC1 by rapamycin decreases primary tumor growth and CXCR4-mediated lymph node metastasis." (PMID 32498358, 2020). "Previous studies of cancer have demonstrated the role that COL3A1 can play in the proliferation of cancer cells, Furthermore, the overexpression of COL3A1 can lead to a significant decrease in the phosphorylation of the AKT/mTOR pathway, a pathway that is important for lactation." (PMID 33101361, 2020). "Thus, cholesterol may provide a link between the mTOR pathway and ERRα/PGC-1 complex activation in cancer cells." (PMID 32717915, 2020). "Increased radioresistance of cancer cells is developed by the activation of several compensatory pro-survival cell signaling pathways, including phosphatidylinositol 3-kinase (PI3K)/AKT/mTOR pathway, EGFR/mitogen-activated protein kinase (MAPK) pathway and NF-κB signaling pathway." (PMID 32983997, 2020). "The signal of mTOR was found to not be involved in ZnO-NPs’ anti-cancer effect." (PMID 32111101, 2020). "However, levels of key intermediates of cancer pro-survival pathways (p-mTOR, p-AKT, and p-ERK) were neither diminished when apoptosis was increased (e.g., in CD151-KO cells), nor elevated when apoptosis was reduced (e.g., in CD151 reconstituted cells)." (PMID 30778617, 2019). "Therefore, it is not recommended to change to mTOR inhibitor–based regimens after a cancer diagnosis." (PMID 30828430, 2019). "In view of the evidence implicating both PI3K and mTOR in cancer, as well as the potential to obtain synergism and address drug resistance, simultaneous inhibition of PI3K and mTOR is expected to provide therapeutic advantages over mono-inhibition of PI3K or mTOR." (PMID 31069214, 2019). "However, RASAL2 also functions as an oncogene in various cancers via the RAS-ERK pathway, phosphoinositide 3-kinase (PI3K)/AKT/mechanistic target of rapamycin (mTOR) signaling pathway, nuclear factor (NF)-κB pathway, and ERK/mitogen activated protein kinase (MAPK) pathway." (PMID 31799194, 2019). "Likewise, water stress proteins (WSP1)-induced autophagy through down-regulating PI3K/AKT/mTOR pathway could degrade β catenin and inhibit EMT through increasing E-cadherin and decreasing N-cadherin, which inhibits cancer migration." (PMID 31126310, 2019).
cancer (continued). "In addition, it is hypothesized that metformin inhibits the mTOR pathway and activation of AMP-activated protein kinase (AMPK), leading to the blockade of cell proliferation in cancer cells." (PMID 31345259, 2019). "The PI3K-Akt-mTOR pathway is involved in the mRNA translation and protein synthesis through EIF4F complex which is activated by most known oncogenes in human cancers and EIF4G1 is an important component of this complex, which helps in the assembly of other components to start the translation." (PMID 31496918, 2019). "Various agents inhibiting the PI3K/AKT/mTOR (PAM) pathway, such as rapamycin, are currently in various stages of clinical development in oncology, ranging from some in early phase evaluations to others that have already received regulatory approval for treatment in advanced cancers." (PMID 31159437, 2019). "Our data suppose that the mTOR–AMPK–ULK1 regulatory triangle, similar to the mTOR–AMPK–NRF2 regulatory module, might be considered as double-edged swords in various diseases, especially in cancer due to their ambiguous role in promoting cell survival in healthy and cancerous cells." (PMID 31703252, 2019). "Inappropriate signal transfer within the cell could lead to pathologies such as cancer, and this dysregulation leads to incorrect signal transmission pathways including PI3K/AKT/mTOR signaling, Wnt signaling, nuclear factor-κB signaling, and many other protein degradation pathways." (PMID 31783627, 2019). "Based on these findings it can be speculated that an ICB treatment unresponsive tumor state is either due to lack of target expression or due to increased PD-L1 expression that imparts aggressive properties to cancer cells via activation of cellular proliferation pathways such as ERK and mTOR." (PMID 31174611, 2019). "Consequently, the clinical improvements of the health status of the animals and of the cancers did not seem to be related to the p-mTOR levels of suppression." (PMID 30863490, 2019). "Consequently, proteins in the PI3K/AKT/mTOR and ERK/MAPK signaling pathways could be good targets for cancer therapy." (PMID 31226829, 2019). "Since mTOR signaling is upregulated in most cancers, the negative control of miR-3178 by mTOR signaling suggests that miR-3178 may be a novel tumor suppressor by targeting CDC6." (PMID 31285446, 2019). "Consequently, the sole inhibition of mTOR may activate PI3K through S6K1 and IRS-1, thus restarting cancer development and mediating drug resistance." (PMID 31069214, 2019). "To ask whether FBXO22 promotes cancer cell growth through LKB1/AMPK/mTOR pathway, we performed further analysis of downstream signaling pathways using p-AMPK(Thr172), p-Raptor(Ser792) and p-P70S6K(Thr389), as indicators of mTOR activation." (PMID 31217475, 2019). "Therefore, combinatorial inhibition of mTOR and CDK1/12 may be synthetically lethal to cancer cells." (PMID 31277692, 2019). "Several studies have indicated that metformin treatment alone can decrease cancer proliferation using HNSCC cell lines, although each study describes a different mechanism of action, including AMPK-independent downregulation of the mTOR pathway or global inhibition of protein translation." (PMID 30621095, 2019). "Therefore, RHOB restoration might benefit cancer prevention and healthspan by antagonizing RAS/PI3K/AKT/mTOR and facilitating Myc turnover." (PMID 31200451, 2019).
cancer (continued). "Nintedanib alone or in combination with Romidepsin, but not Vandetanib, inhibited mTOR signaling suggesting Nintedanib may have broader anti-cancer applicability." (PMID 30701022, 2018). "Analogous to the trend in cancer treatment that have shifted from chemotherapeutic and radiologic regimens to more-host targeted treatment approaches, Mtb infection and/or disease can benefit from specific HDT drugs that targets, for example, the mTOR pathway and/or autophagy." (PMID 29441052, 2018). "Therefore, the mTOR-AKT pathway provides different targets for specific chemotherapeutic agents, with a differential response across different tumors depending on the molecular target itself, as well as the cancer type." (PMID 30323898, 2018). "While the inhibition of mTOR activity as well as activation by the tumor suppressor LKB1 serve as a basis for AMPK’s anti-tumor effects, induction of potentially pro-survival pathways like autophagy and glucose uptake have been proposed to challenge the molecule’s anti-cancer role." (PMID 29534438, 2018). "Analysis of cancer subtypes showed no influence by mTOR inhibitors." (PMID 30473931, 2018). "Moreover, we offer evidence supporting that metformin combined with other clinical metabolic drug targets, such as mTOR and DPP4 inhibitors, could be repurposing as a strategy for treating cancer." (PMID 29899823, 2018). "The need for search of effective multitargeted therapies or broad spectrum approach to cancer treatment fully justifies the attempts to recognize the effect of collective inhibition of the activity of N-cadherin and some crucial signal transducers, such as protein kinases: PI3K, ERK, and mTOR." (PMID 29492694, 2018). "However, the effect of cumulative doses of mTOR inhibitors on cancer after kidney transplantation is not well known." (PMID 30473931, 2018). "The mTOR pathway functions primarily through the PI3K/AKT pathway to activate the tumour cells; members of the PI3K pathway family are frequently altered in human cancers, which leads to cell survival and proliferation, metastasis and activation of some secretion functions." (PMID 29408858, 2018). "Recent in vitro and in vivo studies have suggested that aspirin may suppress cancer cell growth and induce apoptosis through activation of protein kinase A (PRKA, also referred to as AMPK), inhibition of MTOR downstream signaling, and inhibition of PI3K-induced prostaglandin E2 synthesis." (PMID 29152088, 2017). "Various reports have identified cancer relevant pathways, including the vascular endothelial growth factor (VEGF) receptor, the cyclooxygenase-2 (COX-2), epidermal growth factor receptor (EGFR), and mammalian target of rapamycin (mTOR), as EC treatment targets." (PMID 28881819, 2017). "Therefore, tumor-biopsy analyses based on combined mTOR-pathway biomarkers (and combined NGS and IHC assessments) could potentially provide treatment-informative stratification for particular cancer types." (PMID 29137436, 2017). "In particular, in several cancer cells from thyroid, liver, colon, breast, lung, and pancreas, PPAR-γ agonists inhibit IGF-I mediated biological effects through the reduction in Akt phosphorylation, increased PTEN expression levels, and inhibition of mTOR and p70S6K activity." (PMID 28275367, 2017). "p-mTOR overexpression has been reported in cancers of the breast, pancreas, liver, colon, and lung; however, the overall characteristics of p-mTOR expression commonly present in these cancers have not been fully investigated." (PMID 28831205, 2017). "Among its multiple functions, mTOR may favor cancer metabolic reprogramming by activating HIF-1α even under normoxic conditions." (PMID 29190880, 2017).
cancer (continued). "This resulted in the discovery of GDC-0941(compound 13, PI3Kα/β/δ/γ IC50 = 3/3.3/3/7.5 nM, mTOR IC50 = 0.58μM), a potent, selective, orally bioavailable inhibitor of Class I PI3K including the p110α mutant enzymes, and is currently being evaluated in human clinical trials for cancer treatment." (PMID 27769061, 2017). "Our data would suggest that in cancer cells where mTOR activity is not suppressed by DNA damage, CHK1 is maintained and may contribute to enhanced survival." (PMID 28484242, 2017). "However, this latter activity could be counteracted by the hypoxia-induced impairment of mTOR signaling, which not only protects hypoxic HPV-positive cancer cells from the pro-senescent effects of E6/E7 inhibition, but also from pro-senescent CT." (PMID 28678198, 2017). "In line with this, and indicative for sustained mTOR signaling, the amounts of phosphorylated mTOR downstream targets are not (phospho-S6, phospho-p70-S6 kinase) or are only partially (phospho-4E-binding protein 1) reduced when E6/E7 is silenced in HPV-positive cancer cells." (PMID 28678198, 2017). "Yet, it should be emphasized that these considerations do not preclude a therapeutic use of prospective E6/E7 inhibitors, since they would be expected to act in a pro-senescent way in non-hypoxic HPV-positive cancer cells where the therapeutic targets are expressed and mTOR signaling is active." (PMID 28678198, 2017). "In addition, the selective regulation of AKT/mTOR signaling, such as screening for CISD2 expression, might prove valid for cancer treatment when combined with 5‐FU." (PMID 28857517, 2017). "Our study shows that use of mTOR inhibitors together with CNI minimization may be able to offer a reasonable option in view of the relatively stable renal function, very low rejection rate and low cancer recurrence rate." (PMID 28160552, 2017). "Given EGF would activate the PI3K/Akt/mTOR signaling pathway, it is crucial to investigate whether or not MeCDDA can alter the expression level of EGFR on SCLC cells or induce conformational changes in EGF protein structure, achieving its anti-cancer effect." (PMID 28671570, 2017). "For example, salinomycin, a promising anti-cancer drug, induced apoptosis via ROS production, and this mechanism was related to ROS-mediated autophagy through the regulation of the PI3K/Akt/ mechanistic target of rapamycin (mTOR) and ERK/p38 MAPK signaling pathways." (PMID 29065504, 2017). "Based on our results in U2OS cells and our analysis of cancer transcriptomes, it is likely that reduced PML expression observed in these cancers is correlated with reduced DDIT4 expression, which in turn could promote mTOR activation and promote cancer cell growth." (PMID 28332630, 2017). "Interestingly, inhibition of PI3K/mTOR leads to apoptosis of matrix-detached, but not matrix-attached cancer cells, suggesting that matrix-attached cells use alternate mechanisms to maintain nutrient supplies." (PMID 28071763, 2017). "Previous studies suggested that combining a PI3K/Akt/mTOR inhibitor and HDAC inhibitors maybe more effectual than single agents in a number of cancer cells, which represents a translatable and promising approach to cancer therapy." (PMID 28060760, 2017). "Bcl-2 and mTOR are well-known negative regulators of both apoptosis and autophagy while recent evidence indicate that the anti-apoptotic molecule, survivin, also plays a negative modulatory role in autophagy in cancer cells." (PMID 29326587, 2017). "Here, we demonstrated that SHR8443, a novel orally available inhibitor of PI3K/mTOR signaling, exhibited broad antitumor activity against human cancer cell lines independent of their genetic backgrounds both in vitro and in vivo, notably overcoming resistance to targeted anticancer therapies." (PMID 29296217, 2017).